MMP9 (matrix metallopeptidase 9)
Diseases named in the same sentence as MMP9 in open-access papers (continued):
Sharing a sentence is not in itself a finding about the gene and the disease.
ovarian carcinoma (continued). "In addition, ITGAV expression has been correlated with increased expression of the matrix metalloprotease MMP9 in ovarian cancer effusions, which could impact ITGAV shedding into the serum in late stage ovarian cancer." (PMID 35804849, 2022). "Moreover, IHC staining showed the invasion marker MMP-2, MMP-9, Ki67 and PCNA were down-regulated by the loss of LINC00852, suggesting LINC00852 could promote the invasion of ovarian cancer in vivo." (PMID 34496800, 2021). "Therefore, inhibition of S100A11 and MMP-9 expression may further inhibit tumor invasion and metastasis, providing a promising direction in the diagnosis and treatment of ovarian cancer patients." (PMID 33763485, 2021). "Taken together, the data suggest that FBLN5 is degraded in epithelial ovarian cancer possibly by tumor macrophages that support tumor growth by degrading the matricellular protein thereby leading to increased angiogenesis and upregulation of MMP-9 to further support the invasive phenotype of EOC." (PMID 29581841, 2018). "However, other possible tumor metastatic promoting molecules (MMP‐2, MMP‐9) and repressors (E‐cadherin, β‐catenin) could also be involved in the regulation of ovarian cancer metastasis." (PMID 28401704, 2017). "Consequently, MMP-9 has been suggested as a potential serum marker for ovarian cancer diagnosis, and high serum MMP-9 level might be a predictor for refractory tumors." (PMID 28538838, 2017). "Thus, Rap1A may promote ovarian cancer metastasis at least partially through the up‐regulation of MMP9." (PMID 27925454, 2016). "Additionally, AXL has been shown to regulate MMP-1, MMP-2 and MMP-9 expression in ovarian cancer." (PMID 27764792, 2016). "Furthermore, some studies suggest that CLU may regulate aggressive behavior of human clear renal cell cancer (CRCC), ovarian cancer, and colon cancer cells through MMP-9 or VEGF expression." (PMID 26716898, 2016). "Thus, the inhibitory activity of PMBPs on the invasiveness of ovarian cancer might be, at least partially, due to the suppression of MMP-9 activity." (PMID 26539720, 2015). "As the pioneering data to demonstrate PMBPs' efficacy to trigger apoptosis by activating the mitochondria-associated apoptotic pathway and to inhibit cell migration and invasion via MMP-9 down-regulation, PMBPs could be developed as a novel effective anti-tumor agent for ovarian cancer treatment." (PMID 26539720, 2015). "Therefore, PMBPs may suppress MMP-9 activity to impair the migration and invasion capabilities of ovarian cancer cells." (PMID 26539720, 2015). "Collectively, these different signaling paradigms involved with EMT in ovarian cancer suggest that growth factor receptor glycosylation modification involving the receptor-signaling platform of a Neu1-MMP-9 crosstalk may in fact be the invisible link connecting the Snail-MMP-9 signaling axis." (PMID 26932374, 2014). "Together these data support a model wherein LPA induces MMP-9 expression and MMP-9-catalyzed E-cadherin ectodomain shedding, resulting in loss of E-cadherin junctional integrity and epithelial cohesion, facilitating metastatic dissemination of ovarian cancer cells." (PMID 22593767, 2012). "Impact statement This work provides direct evidence that MMP9 mediates EGF-driven membrane protrusions and promotes ovarian cancer cell adhesion to mesothelial extracellular matrices." (PMID 41732872, 2026). "Together, these results provide direct evidence that MMP9 mediates EGF-driven membrane protrusions and promotes ovarian cancer cell adhesion to mesothelial extracellular matrices." (PMID 41732872, 2026). "To further understand the contribution of MMP9 to EGF-stimulated metastatic behavior, we created MMP9-null cells (M9-KO) from an ovarian cancer cell line." (PMID 41732872, 2026). "In ovarian cancer, RBP4 overexpression stimulates the expression of MMP-2 and MMP-9, which increases the migration of tumor cells and affects the unfavorable prognosis." (PMID 41007818, 2025).
ovarian carcinoma (continued). "In contrast, WFDC4 promotes metastasis in ovarian cancer via PI3K-AKT pathway activation and MMP-9 secretion." (PMID 40350979, 2025). "The compound formulation inhibits ovarian cancer cell invasion and metastasis by down-regulating the protein expression of HIF-α, MMP-2, MMP-9, and E-cadherin, demonstrating significantly in vivo pharmacodynamic effects." (PMID 40490812, 2025). "In ovarian cancer cell lines SKOV-3 and OVCAR-3, Ex-4 induces apoptosis by modulating NF-κB downstream targets, including matrix metalloproteinase-9 (MMP-9), intercellular adhesion molecule-1(ICAM-1), BAX, Bcl-2, and cyclin D." (PMID 40140925, 2025). "Previous work suggested SOX2 regulates tumorigenic features and EMT processes by modulation of MMP2 and MMP9 activity in human CRC and ovarian cancer cells." (PMID 40179020, 2025). "A Venn diagram revealed 30 overlapping targets between hydnocarpin and ovarian cancer, including key genes such as MMP2 and MMP9." (PMID 40722951, 2025). "WFDC4, predominantly studied in ovarian cancer, affects tumor invasion and metastasis by regulating the PI3K-AKT signaling pathway and MMP-9 secretion." (PMID 39296934, 2024). "Most of the tested metalloproteinases upregulated mRNA expression in both FIGO I/II and FIGO III/IV stages of ovarian cancer (MMP1, MMP13, MMP2, MMP9, MMP10, MMP7, MMP12 and MMP14) indicating profound modifications of the extracellular matrix." (PMID 38397798, 2024). "Recently, levels of matriptase, a transmembrane serine protease, were shown elevated in ovarian cancer, acting via the activation of PAR2 inducing the signaling of PI3K/Akt and MMP9 promoted the dislodging of cell–cell contacts." (PMID 38275417, 2024). "Based on the results of the experiments and bioinformatics analyses, it is inferred that the target gene CENP-O exerts its effects in ovarian cancer cell disease by regulating genes such as AKT2, JAK2, and MMP9 in SK-OV-3 cells." (PMID 38890751, 2024). "The results demonstrated that melatonin inhibited the invasion and migration abilities of ovarian cancer SKOV3 cells while up-regulating E-cadherin expression and down-regulating MMP-9, vimentin, and VEGF protein expressions." (PMID 38751791, 2024). "PAM can inhibit the in vitro and in vivo metastasis of ovarian cancer cells by blocking the activation of the mitogen-activated protein kinase (MAPK) pathway and reducing MMP-9 secretion." (PMID 39769029, 2024). "FMN has been shown to alleviate ovarian cancer in SKOV-3 cells by increasing E-cadherin expression and decreasing MMP-9 expression, which inhibits the cancer cell proliferation, migration, and invasion." (PMID 37680711, 2023). "According to Zhu, harmine was able to inhibit cell migration by reducing MMP-2 and MMP-9 expression levels in glioblastoma, and Gao reported that harmine inhibited MMP-9 expression in ovarian cancer cells." (PMID 37175359, 2023). "There is increasing evidence that RBP4 is associated with cancer development; for example, high levels of RBP4 promote the migration and proliferation of ovarian cancer cells through stimulation of MMP2 and MMP9 expression." (PMID 37313408, 2023). "In accordance with the previous reports of MMP expression for the progression of the ovarian cancer, we have tested the effect of DNC, Oxa, and its combination on the differential expression of MMP-2 and MMP-9." (PMID 36658640, 2023). "In ovarian cancer, TP73‐AS1 was showed to promote cell survival and metastasis via increasing MMP2 and MMP9 expressions." (PMID 35871358, 2023). "Other groups have corroborated the data, showing that treatment with RNA interference or antigelatinolytic peptides against MMP-9 affected the invasive behavior of OSCC and ovarian cancer cells." (PMID 36674806, 2023). "Luteolin had been reported to inhibit ovarian cancer metastasis by downregulating MMP2 (Matrix Metallopeptidase 2) and MMP9 (Matrix Metallopeptidase 9)." (PMID 36483919, 2022).
ovarian carcinoma (continued). "By regulating cyclinD1, MMP9 and p27, knockdown of S100A7 reduces epithelial ovarian cancer (EOC) cell proliferation, migration and invasion, and enhances chemosensitivity to cisplatin." (PMID 36077500, 2022). "Upregulation of VCAN in CAFs enhanced ovarian cancer cell motility and invasion potential by activating the NF-κB signaling pathway and upregulated expression of CD44, MMP9 and the hyaluronan mediated motility receptor." (PMID 36203562, 2022). "For example, lancemaside A, isolated from Codonopsis lanceolata, inhibits the metastasis of ovarian cancer cells and decreases the MMP2 and MMP9 expression levels." (PMID 35621926, 2022). "In ovarian cancer cells, overexpressing of HK2 enhanced cell motility by inducing of EMT-related proteins, such as CDH2, fibronectin, MMP9, ZEB1, ZEB2 and vimentin." (PMID 35953860, 2022). "VEGFA, PLAU, MMP2, MMP9, and MMP14 expression levels were reduced by stigmasterol treatment, which exerted a complex anticancer effect in the context of ovarian cancer." (PMID 35379271, 2022). "The GSK-3β inhibitor AZD1080 suppresses ovarian cancer cell proliferation, invasion, and migration and downregulates GSK-3β, MMP9, and Bcl-xL mRNA and proteins." (PMID 35723293, 2022). "In particular, MMP2 and MMP9 can degrade collagen IV, the major ECM component, and play important roles in ovarian cancer." (PMID 35621926, 2022). "In ovarian cancer, activated EGFR upregulates MMP-9 which sequentially promotes the degradation of E-cadherin molecules resulting in metastasis." (PMID 34912809, 2021). "Knockdown of endogenous GSK3β in ovarian cancer cells inhibited both phospho-ETS1 and MMP-9 expression." (PMID 34023818, 2021). "In ovarian cancer, the expression levels of vascular endothelial growth factor (VEGF) and MMP9 are downregulated following CD147 knockdown." (PMID 33390850, 2021). "Overexpression of MMP-9, together with the imbalance between MMP-9 and TIMP-1, play an important role in the development of ovarian cancer, when the blood serum level of TIMP-1 is elevated." (PMID 34572929, 2021). "Abnormal expression of UCA1 promotes the invasion and metastasis of ovarian cancer cells by up-regulating matrix metalloproteinase (MMP) 2 and MMP9." (PMID 34233576, 2021). "Co-culture of human omental ADSCs and SKOV3 ovarian cancer cells increased cancer cell proliferation and migration via an increased ADSC secretion of MMP-9 and MMP-2." (PMID 34440886, 2021). "Because we have previously shown that LY2090314 can inhibit murine ovarian cancer-MOSEC cells growth, we also examined the endogenous ETS1 and MMP-9 protein levels in the same experimental tumors of LY2090314-treated mice." (PMID 34023818, 2021). "The silencing of MMP9 reduced the effects of TP73-AS1 overexpression on cell invasion and migration in ovarian cancer." (PMID 34067437, 2021). "CQDs/Cu2O selectively mediated of ovarian cancer SKOV3 cells death mainly through downregulation the expression of MMP-2, MMP-9, F-actin, and VEGFR2, meanwhile CQDs/Cu2O induced apoptosis of SKOV3 via S phase cell cycle arrest." (PMID 33663548, 2021). "In ovarian cancer, silencing HOTAIRM1 promoted cell proliferation and inhibited cell apoptosis by regulating the Wnt pathway and its downstream target gene MMP9." (PMID 35087800, 2021). "In ovarian cancer, VEGF induces ETS1 expression by activating the PI3K/Akt and p38MAPK signaling pathways, which further activates MMP9 and MMP13 and promotes SKOV3 invasion and metastasis." (PMID 34659572, 2021). "It has also been shown that the expression of MMP-9 and TIMP-1 induced by the epidermal growth factor (EGF) in ovarian cancer cell lines results in increased migration and mass spread induced by EGF." (PMID 34572929, 2021). "The role of VEGF-VEGFR in invasion and migration of ovarian cancer is proven in vitro through the secretion and activation of Matrix Metalloproteinase-2 (MMP-2), MMP-7, MMP-9 and urokinase type plasminogen activators." (PMID 33639643, 2021).
ovarian carcinoma (continued). "In ovarian cancer cells, VEGF enhances the expression of host MMP-9 in the ovaries due to an increased influx of neutrophils that secrete MMP-9, demonstrating a potential feedback mechanism between VEGF and MMPs." (PMID 33810259, 2021). "Norepinephrine and E can directly increase the invasive ability of ovarian cancer cells through upregulation of MMP-2 and MMP-9 via ADRB2." (PMID 34307378, 2021). "The MMP-2 inhibition by presence of TCF21 in ACC cells was also reported in colon rectal and ovarian cancer cells, showing the TCF21 properties in decrease cell invasion of different types of tumors through inhibition of MMP-9 and MMP-2." (PMID 35201460, 2021). "Specifically, our study findings are in line with a recent study showing that two bioactive compounds of pomegranate namely ellagic acid and luteolin prevent proliferation and migration of ovarian cancer cells by reducing the expression of MMP-2 and MMP-9." (PMID 32224968, 2020). "In epithelial ovarian cancer, C3G (Rap1GEF1)-induced Rap1 activation promoted the secretion of MMP2 and MMP9." (PMID 32906721, 2020). "In addition, MMPs such as MMP2 and MMP9 could be prognostic biomarkers for ovarian cancer." (PMID 33024414, 2020). "Studies have shown that activation of STAT3 in ovarian cancer leads to upregulation of MMP2 expression, and inhibition of STAT3 in pancreatic cancer cells results in down-regulation of MMP9 expression." (PMID 33292347, 2020). "The TAMs in ovarian cancer patients express elevated VEGF and MMP-9 because of the high psychological stress levels (e.g., chronic life stress, depression, and perceived stress)." (PMID 33392191, 2020). "In contrast, the inhibition of SERPIND1 expression in ovarian cancer cells reduced the phosphorylation of PI3K/AKT, increased E-cadherin expression, and reduced the expressions of N-cadherin, Vimentin, MMP2, and MMP9." (PMID 31637210, 2019). "GEPIA further revealed a significant clinical correlation between MMP9, uPA, and VEGF and HK2 expression (p < 0.05) in ovarian cancer clinical samples." (PMID 31212816, 2019). "These CAF-related molecules further confer the aggressiveness of ovarian cancer cells through the activation of NF-κB signaling pathway and the up-regulation of CD44, MMP9 and hyaluronan-mediated motility receptor (HMMR)." (PMID 31888563, 2019). "Western blot analyses showed that knockdown of HE4 reduced the levels of matrix metalloproteinases (MMP-2 and MMP-9) and inhibited epithelial to mesenchymal transition (EMT) in ovarian cancer cells." (PMID 31477564, 2019). "To further analyze the role of SERPIND1 in ovarian cancer cells, we examined the major proteins of epithelial–mesenchymal transition (EMT), including MMP2, MMP9, Vimentin, N-cadherin, and E-cadherin." (PMID 31637210, 2019). "In conclusion, HK2, which is regulated by the tumor microenvironment, controls lactate production and contributes to ovarian cancer metastasis and stemness regulation via FAK/ERK1/2 signaling pathway-mediated MMP9/NANOG/SOX9 expression." (PMID 31212816, 2019). "In this study, we have demonstrated that deoxyschizandrin inhibits M2 polarization and production of protumoural factors MMP-9, RANTES, and VEGF in macrophages stimulated by ovarian cancer cells." (PMID 29342940, 2018). "Until now, well known MMPs which levels correlate with ovarian cancer are levels of MMP2, MMP7 and MMP9." (PMID 29304854, 2018). "EGF induced MMP-9 and TIMP-1 expression in ovarian cancer cell lines has been shown to result in increased migration and robust EGF-induced invasion." (PMID 29393911, 2018). "The MMP-2, MMP-3, and MMP-9 expression levels were next examined in the cocultivation of SKOV3 and WS1 to mimic the interaction of ovarian cancer cell with stromal cells." (PMID 29390034, 2018). "Our findings suggest that E2F1 functions as an oncogene in ovarian carcinoma in part by upregulating Bcl-2, cyclin D1, survivin, MMP2, and MMP9 expression." (PMID 28146423, 2017).
ovarian carcinoma (continued). "Our results showed that MMP-2, MMP-7, MMP-9 and MMP-10 expression were significantly up-regulated in ovarian cancer tissue compared with normal ovarian tissues." (PMID 28476165, 2017). "In conclusion, EZH2 promotes ovarian cancer migration and invasion via the epigenetic silencing of TIMP2 by H3K27me3 and DNA hypermethylation, which leads to the activation of MMP2 and MMP9." (PMID 28620234, 2017). "This suggests that miR-519d has suppressive effects on ovarian carcinoma by downregulating RhoC, Bcl-2, cyclin D1, survivin, MMP2, MMP9, STAT3 and HuR expression." (PMID 28146423, 2017). "NEAT1 knockdown in ovarian cancer cells resulted in a decrease in Snail1, TGF-β1, MMP-2 and MMP-9 and so presumably promotes EMT in ovarian cancer." (PMID 28430163, 2017). "VEGF regulates ovarian cancer invasion and migration in vitro through VEGFR-mediated secretion and activation of MMP-2, MMP-7, and MMP-9." (PMID 28476025, 2017). "Exposing vesicles released by ovarian cancer cells (CABA1) to acidic medium increased MMP-2 and MMP-9 activities; this effect was abolished by the specific inhibitor of cystein protease or by silenced expression of cathepsin B in CABA1 cells." (PMID 28317069, 2017). "We found that miR-519d transfection decreased MMP2, MMP9, STAT3, and HuR expression in ovarian carcinoma cells; at the same time, E2F1 increased the expression of these genes." (PMID 28146423, 2017). "Overexpression of HIF‐1α upregulated AEG‐1 expression and enhanced migration of ovarian cancer cells by inducing the expression of MMP2 and MMP9 as well as inhibiting the expression of E‐cadherin and β‐catenin." (PMID 28401704, 2017). "Our results suggested that HIF‐1α binds to AEG‐1 promoter to upregulate its expression, which was correlated with metastasis in ovarian cancer by inducing the expression of MMP2 and MMP9 as well as inhibiting expression of E‐cadherin and β‐catenin." (PMID 28401704, 2017). "In conclusion, our study identifies a novel molecular mechanism for E2F1, whereby it targets miR-519d to upregulate RhoC, Bcl-2, cyclin D1, survivin, MMP2, MMP9, STAT3 and HuR expression, promoting tumorigenesis and progression in ovarian carcinoma." (PMID 28146423, 2017). "Recent data also suggested that C3G, acting through Rap1, induces invasion of epithelial ovarian cancer cells and promotes the secretion of matrix metalloproteases MMP2 and MMP9." (PMID 27286263, 2016). "Activation of the Shh pathway induces the expression of MMP-9 in pancreatic cancer cell lines and MT1-MMP expression in ovarian cancer cell lines." (PMID 26859575, 2016). "Recent published data also suggest that C3G, acting through Rap1, promotes invasion of epithelial ovarian cancer cells through induction of MMP2 and MMP9 secretion." (PMID 27286263, 2016). "Matrix metalloproteinases (MMPs) secreted by cervical and ovarian cancer, especially MMP-2 and MMP-9, play crucial roles in tumor invasion and metastasis." (PMID 25686833, 2015). "Accordingly, Axl knockdown in ovarian cancer SKOV3 cells has been shown to reduce PI3K/Akt activation and the expression of MMP-1 and MMP-9, both in vitro and in vivo using the peritoneal xenograft model of ovarian cancer." (PMID 26356564, 2015). "We found up-regulation of MMP9 by PITX2 in ovarian cancer cells, suggesting PITX2 as a key regulator of relevant genes that control invasion/metastasis of ovarian cancer cells." (PMID 26298390, 2015). "When CD147 is silenced in ovarian carcinoma cells, both VEGF and MMP-9 mRNA or protein are down-regulated, while CD147 expression negatively affects basic fibroblast growth factor (bFGF) expression." (PMID 25268615, 2014). "We report a successful adaptation of HCS for cytotoxicity using a novel MMP-9/MMP-2i alone and in combination with cisplatin and we provide evidence regarding highly selective MMP-9/MMP-2i involvement in the treatment of ovarian cancer." (PMID 23340649, 2013).